RN7SKP263 (RN7SK pseudogene 263)
Gene: Miscellaneous RNA gene on chromosome 12 (94,008,739 to 94,009,047, reverse strand). Ensembl gene ENSG00000223126.
Homologues: Orthologues: chimpanzee 7SK (99% identical), guinea pig 7SK (61% identical). Paralogues in human: RN7SKP162 (72% identical), RN7SKP180 (71% identical), RN7SKP133 (71% identical), RN7SKP176 (70% identical), RN7SKP184 (70% identical), RN7SKP189 (70% identical), RN7SKP79 (70% identical), RN7SKP9 (70% identical), RN7SKP77 (70% identical), RN7SKP124 (69% identical), RN7SKP90 (69% identical), RN7SKP97 (69% identical), and 283 more.